RNU6-911P (RNA, U6 small nuclear 911, pseudogene)
Gene: Small nuclear RNA gene on chromosome 7 (139,448,740 to 139,448,843, forward strand). Ensembl gene ENSG00000252332.
Homologues: Orthologues: chimpanzee U6 (99% identical), macaque U6 (86% identical), rat LOC120100203 (50% identical). Paralogues in human: RNU6-315P (73% identical), RNU6-38P (73% identical), RNU6-874P (73% identical), RNU6-1011P (72% identical), RNU6-1117P (72% identical), RNU6-187P (72% identical), RNU6-275P (72% identical), RNU6-338P (72% identical), RNU6-429P (72% identical), RNU6-476P (72% identical), RNU6-682P (72% identical), RNU6-799P (72% identical), and 1287 more.